CAPN2 (calpain 2)
Diseases named in the same sentence as CAPN2 in open-access papers (continued):
Sharing a sentence is not in itself a finding about the gene and the disease.
ischemia (3 papers, 2014 to 2021). A hypoperfusion of the BLOOD through an organ or tissue caused by a PATHOLOGIC CONSTRICTION or obstruction of its BLOOD VESSELS, or an absence of BLOOD CIRCULATION. "A recent study showed that inhibition of calpain 2 ameliorated retinal ischemic injury, suggesting that calpain-2 inhibitor might prevent ischemia-induced retinal degeneration." (PMID 33654115, 2021). "We then investigated whether calpain-2 over-activation/-expression could be antagonized by calpain-specific inhibitor MDL28170, a known neuroprotective substrate in ischemia and traumatic injury models." (PMID 25341622, 2014).
osteosarcoma (3 papers, 2013 to 2025). A usually aggressive malignant bone-forming mesenchymal neoplasm, predominantly affecting adolescents and young adults. "In our study, the expression of calpain 1 and calpain 2 was first examined, and the results showed that calpain family proteins were clearly present in all osteosarcoma cell lines." (PMID 40959067, 2025). "A previous report showed that calpain 1 and calpain 2 were involved in the adhesive and invasive abilities of osteosarcoma cells by affecting MMP-2 secretion." (PMID 23855590, 2013). "However, calpain 1 and calpain 2 seem to play a more sophisticated role in osteosarcoma, which is shown with the opposite effects in 143B cell lines." (PMID 40959067, 2025). "In human osteosarcoma U2-OS and cervical cancer HeLa cell lines, TMBIM4 is considered a novel regulator of focal adhesion dynamics, cell adhesion, and migration by activating store-operated Ca2+ entry, thereby stimulating calpain 2 activity to increase the cleavage of focal adhesion proteins." (PMID 36829486, 2023).
renal cell carcinoma (3 papers, 2017 to 2025). "For instance, depletion of CAPN2 inhibits cell metastasis and proliferation in renal cell carcinoma." (PMID 35707527, 2022). "Depletion of CAPN2 could inhibit the expression of N-cadherin, vimentin and MMP9, and overexpression of CAPN2 could enhance N-cadherin, vimentin and MMP9 protein levels in renal cell carcinoma." (PMID 35707527, 2022).
Sepsis (3 papers, 2020 to 2023). Sepsis is defined as life-threatening organ dysfunction caused by a dysregulated host response to infection. "Sepsis increased the expression of calpain-2 mRNA and pro-inflammatory protein calpain-2 and p-STAT3 compared with those in the control group." (PMID 36160853, 2022). "However, the role of calpain-2 in sepsis-associated cardiomyopathy is largely unknown." (PMID 36160853, 2022). "Thus, in this study, we aimed to investigate the protective effect of EA pre-treatment against sepsis cardiomyopathy and the potential role of calpain-2/STAT3 signalling in process ofinflammation and apoptosis." (PMID 36160853, 2022). "In sepsis, the role of calpain-2-regulated STAT3 in cardio-protective mechanism of electroacupuncture remains unclear." (PMID 36160853, 2022). "Elucidating the role of calpain-2 in the pathological process of sepsis-induced cardiac inflammation will be required to better understand the effect of EA protection, which may not only help understand the molecular mechanism of EA but also have potential clinical value." (PMID 36160853, 2022). "In summary, to the best of our knowledge, this is the first study to report that EA pre-treatment downregulates calpain-2 expression, thereby inhibiting the phosphorylation of STAT3 and improving cardiac function during sepsis." (PMID 36160853, 2022).
amyotrophic lateral sclerosis (2 papers, 2022 to 2024). Amyotrophic lateral sclerosis (ALS) is a neurodegenerative disease characterized by progressive muscular paralysis reflecting degeneration of motor neurons in the primary motor cortex, corticospinal tracts, brainstem and spinal cord. "Calpain-2 is shown to be involved in the breakdown of α-syn in PD and huntingtin protein in Huntington’s disease (HD), and it cleaves TDP43 proteins implicated in motor neuron function in Amyotrophic Lateral Sclerosis (ALS)." (PMID 38791036, 2024). "Moreover, several potential disease-causing genes were detected and markedly enriched in the pathways of neurodegeneration (including WNT16, RYR3 and RYR1 genes) and amyotrophic lateral sclerosis (ALS, including NUP205, CAPN2, and NUP214 genes)." (PMID 35355568, 2022).
Cerebral ischemia (2 papers, 2020 to 2021). Restriction of arterial blood supply to the brain associated with insufficient oxygenation to support the metabolic requirements of the tissue. "It has been reported that Ca2+ overload leads to neuronal apoptosis through calpain-2, when cerebral ischemia and hypoxia occur." (PMID 34604209, 2021).
chronic kidney disease (2 papers, 2022 to 2025). Impairment of the renal function secondary to chronic kidney damage persisting for three or more months. "This study demonstrates that calpains, particularly CAPN2, play a central role in muscle deterioration associated with chronic kidney disease (CKD)." (PMID 41369335, 2025).
cognitive deficits (2 papers, 2018 to 2023). "We further demonstrated that a relatively selective calpain-2 inhibitor prevented calpain-2 activation, reduced neuronal damage, prevented motor and cognitive impairment, and reduced the levels of blood biomarkers reflecting brain calpain-2 activation." (PMID 37474874, 2023). "To summarize, our results have clearly demonstrated that calpain-2 activation remains elevated for days after TBI and is responsible for the brain damage and associated motor and cognitive impairments resulting from the trauma." (PMID 37474874, 2023). "Next, we assessed calpain-2 protein levels in synaptosomes and PNS fractions isolated from frontal neocortical tissue from post-mortem brains of persons with AD dementia compared to subjects with no cognitive impairment (NCI) and mild cognitive impairment (MCI)." (PMID 30177812, 2018).
diabetes (2 papers, 2016 to 2023). "Calpain-1 and calpain-2 protein expression and activity in cardiac mitochondria is known to be increased in diabetes leading to myocardial injury and dysfunction." (PMID 37569859, 2023). "We thereby concluded that CaN together with its upstream molecule, calpain 2, and its downstream effector, NFAT-c3, might contribute to the development of AF in patients with VHD and diabetes." (PMID 27123462, 2016). "Thus, our current study investigated the role of calpain 2-CaN-NFAT pathway in mediating the development of AF in the patients with VHD and diabetes." (PMID 27123462, 2016). "The expressions of calpain 2 and alpha- and beta-isoforms of CaN catalytic subunit (CnA) as well as NFAT-c3 and NFAT-c4 were quantified by quantitative reverse transcription-polymerase chain reaction in atrial tissues from 77 hospitalized patients with VHD and diabetes." (PMID 27123462, 2016). "Our results indicated that the gene expressions of calpain 2, CaN, and NFAT-c3 but not NFAT-c4 were significantly increased in the left atrial tissue of AF patients with VHD and diabetes compared to those with SR." (PMID 27123462, 2016).
gastric cancer (2 papers, 2021 to 2022). A primary or metastatic malignant neoplasm involving the stomach. "In contrast to calpain-1 and calpain-2 isoforms, the downregulation of calpain-9 expression was associated with metastasis in patients with gastric cancer, suggesting the protective effect of calpain-9 expression and its roles in hampering gastric cancer progression." (PMID 33430230, 2021). "It has been reported that CAPN2 is involved in the development of a variety of tumors, including liver cancer, gastric cancer and so on." (PMID 35783277, 2022).
glaucoma (2 papers, 2024 to 2025). Increased pressure in the eyeball due to obstruction of the outflow of aqueous humor. "Specifically, calpain-2 has been connected to NIV, cataractogenesis, and glaucoma, while calpain-5 was associated with NIV and uveitis." (PMID 38303059, 2024).
glomerulosclerosis (2 papers, 2020 to 2022). A hardening of the kidney glomerulus caused by scarring of the blood vessels. "Calpain 1 and Calpain 2 activities are closely linked to both renal inflammatory response and aging, and suppression of Calpain 1 and 2 has been shown to relieve glomerulosclerosis and proteinuria." (PMID 35155498, 2022). "Podocyte-specific deletion of Capns1, essential for calpain-1 and calpain-2 activities, also improved proteinuria and glomerulosclerosis in Gak-KO mice." (PMID 33208557, 2020).
Hepatic fibrosis (2 papers, 2021 to 2024). The presence of excessive fibrous connective tissue in the liver. "CAPN2 expression was discovered to be an indicator of level of hepatic fibrosis during hepatitis B virus infection." (PMID 38349185, 2024). "CAPN2, as a subtype of CAPN, played a crucial role in the expression of hepatic fibrosis markers, including COL3A1, COL1A1 and MAPK1." (PMID 33836021, 2021).
injury (2 papers, 2021 to 2024). Damage inflicted on the body as the direct or indirect result of an external force, with or without disruption of structural continuity. "Selective calpain-2 inhibitors have been synthesized and clinical studies to test their potential use to treat disorders associated with acute neuronal damage, such as traumatic brain injury, are being planned." (PMID 38361744, 2024). "In terms of interaction with serious complications in COVID‐19 patients, 6 markers (MFAP4, ECM1, CDKN2B.AS1, CAPN2, FGG, and CD147) and 2 exRNAs (SNORD33 and miR‐122‐5p) are involved in thrombosis or liver injury." (PMID 34122778, 2021).
Insulin resistance (2 papers, 2023 to 2024). Increased resistance towards insulin, that is, diminished effectiveness of insulin in reducing blood glucose levels. "However, whether the mechanisms underlying the role of CAPN2 in insulin resistance are identical to those of CAPN10 warrants further in-depth investigation." (PMID 38610028, 2024). "This study highlights the pivotal role of CAPN2 in insulin resistance within the context of PCOS, emphasizing its importance as both a critical biomarker and a potential therapeutic target." (PMID 38610028, 2024). "Our research introduces the concept of a significant correlation between CAPN2 and insulin resistance, akin to that observed with CAPN10." (PMID 38610028, 2024). "By identifying CAPN2, our research contributes to the expanding evidence surrounding the CAPN family, particularly CAPN10, in insulin resistance studies beyond PCOS." (PMID 38610028, 2024). "Metformin may inhibit the release of calpain 2 from exosomes, interfere with IR splitting (through the pathway of knocking out calpain 2 and γ-secretase), restore the functions of IRS-1 and Akt, and re-establish insulin signaling, thereby alleviating insulin resistance, enhance insulin sensitivity." (PMID 36818396, 2023).
liver cancer (2 papers, 2022 to 2024). An epithelial or non-epithelial malignant neoplasm that arises from the liver. "Intriguingly, we found CAPN2 protein expression was positively correlated with YWHAE protein expression in liver cancer cell lines according to CCLE database." (PMID 39739077, 2024).
lung fibrosis (2 papers, 2018 to 2025). "Lastly, while CAPN2 showed a dispersed expression pattern, it was notably activated in epithelial cells, and calpain signaling pathways involving CAPN2 have been implicated in the development of pulmonary fibrosis." (PMID 40750896, 2025). "Likewise, the protein levels of calpain-1, calpain-2 were increased, suggesting that BLM-induced calpain activation in lung fibrosis." (PMID 29666896, 2018).
metastatic prostate carcinoma (2 papers, 2021). A carcinoma that arises from the prostate gland and has spread to other anatomic sites. "Moreover, CAPN2 is also related to metastatic prostate cancer by potentiating proliferative and invasive capabilities." (PMID 33731671, 2021).
Parkinson disease (2 papers, 2022 to 2026). A progressive degenerative disorder of the central nervous system characterized by loss of dopamine producing neurons in the substantia nigra and the presence of Lewy bodies in the substantia nigra and locus coeruleus. "Overall, our study suggests that the inhibition of calpain, especially calpain-2, attenuates glial activation, promotes microglial differentiation into M2 cells, prevents neurodegeneration, and rescues neurons in rotenone parkinsonism." (PMID 36430329, 2022).
status epilepticus (2 papers, 2025). Status epilepticus is defined as a continuous seizure lasting more than 30 min, or two or more seizures without full recovery of consciousness between any of them. "In the hippocampus of pilocarpine-induced status epilepticus (PISE) mice, the ratio of inactive calpain 1 protein level to its total protein level (inactive/total calpain 1) significantly decreased, while the ratio of inactive calpain 2 protein level to its total protein level remained unchanged." (PMID 40205503, 2025).
tauopathies (2 papers, 2018 to 2025). "For instance, Tau cleavage by calpain 2 produces a 17 kDa neurotoxic fragment, and significant amounts of these fragments are found in the brains of patients with tauopathy." (PMID 29982852, 2018).
age-related macular degeneration (1 paper, 2023). Age-related loss of vision in the central portion of the retina (macula), secondary to retinal degeneration. "In summary, these results demonstrate for the first time that calpain-2 is one of the key players in the NaIO3-exo-mediated ALP dysfunction, apoptosis, and retinal damage and identify calpain-2 as a promising target for therapies aimed at age-related macular degeneration (AMD)." (PMID 36703913, 2023).
ampullary cancer (1 paper, 2012). "The expression of calpain-1, calpain-2 and calpastatin cytoplasmic and nuclear expression was tested to determine associations with clinicopathological criteria in the pancreatic and the grouped bile duct and ampullary cancers." (PMID 23140395, 2012). "In the bile duct and ampullary carcinomas calpain-1 expression had a statistically significant correlation with cytoplasmic calpastatin expression (r = 0.425, P < 0.001) and nuclear calpastatin expression (r = 0.295, P = 0.002), but not with calpain-2 expression." (PMID 23140395, 2012).
aortic aneurysm (1 paper, 2013). A ruptured aneurysm located in the wall of the proximal portion of the descending aorta proceeding from the arch of the aorta. "Calpain-2 compensates for loss of calpain-1, and both calpain isoforms are involved in AngII-induced aortic aneurysm formation in mice." (PMID 23977256, 2013).
cancers of the bile duct (1 paper, 2012). "In summary, this study demonstrates that low expression of calpain-2 is associated with poor survival in pancreatic cancer and low cytoplasmic calpastatin expression is associated with poor survival in cancers of the bile duct and ampulla." (PMID 23140395, 2012).
cardiac hypertrophy (1 paper, 2022). "Calpain-2 catalytic subunit and lumican related to cardiac fibrosis, and mitogen-activated protein kinase 12 (MAPK12) related to cardiac hypertrophy, showed a significantly negative correlation with CO and TAPSE, and a significantly positive correlation with RV/BW." (PMID 35865003, 2022).
chronic myeloid leukemia (1 paper, 2017). "However, some studies showed that calpain-1 and calpain-2 play opposite roles in retinal ischemia/reperfusion injury but both, calpain-1 and calpain-2, provide neuroprotection in chronic myeloid leukemia." (PMID 29036897, 2017).
Cluster headache (1 paper, 2022). A type of headache characterized by repeated attacks of unilateral pain lasting 15 to 180 minutes and associated with local autonomic signs. "We identified three susceptibility loci, in CAPN2, MERTK, and SATB2, as well as one suggestive locus at CYP2C18/CYP2C19 at genome-wide level in patients with cluster headache in Taiwan." (PMID 36404298, 2022). "Another potential implication of CAPN2 may be that the most commonly used preventive drug for cluster headache, the L-type calcium channel blocker verapamil, has been known to abrogate calpain activation." (PMID 36404298, 2022).
colorectal tumour (1 paper, 2019). "Calpain-2, also known as m-calpain when bound to its regulatory subunit calpain-S1, is over expressed in colorectal tumour cells." (PMID 31217905, 2019).
Crohn's colitis (1 paper, 2025). Crohn's disease affecting the colon. "This study elucidates a pathogenic pathway in which ITLN1 competitively binds TRIM8 to inhibit CAPN2 ubiquitination and degradation, stabilizing CAPN2 to promote ZBP1-mediated PANoptosis in IECs and exacerbate Crohn's colitis." (PMID 40520022, 2025).
dementia (1 paper, 2018). Loss of intellectual abilities interfering with an individual's social and occupational functions. "Moreover, synaptosomal calpain-2 was hyperactivated in frontal neocortical tissue samples of post-mortem brains of AD-dementia subjects and correlated significantly with decline in tests for cognitive and memory functions, and increase in levels of β-amyloid deposits in brain." (PMID 30177812, 2018).
diabetic retinopathy (1 paper, 2021). "The underlying molecular processes of SST- and PACAP-receptor signaling include the inhibition of proapoptotic molecules (e.g., caspase-3, caspase-8, FasL and calpain-2), meaning that they could be very well suited for reducing the harmful effects of diabetic retinopathy." (PMID 33466261, 2021).
dilated cardiomyopathy (1 paper, 2024). Cardiomyopathy which is characterized by dilation and contractile dysfunction of the left and right ventricles. "Sustained over-expression of calpain-2, specifically in cardiomyocytes, induced age-dependent dilated cardiomyopathy in mice." (PMID 38438525, 2024).
disc degeneration (1 paper, 2021). "This illustrated that LPS induced ER stress-mediated apoptosis through the calpain-2/caspase-12-dependent pathway in NPCs, thus leading to NPC apoptosis and subsequently disc degeneration." (PMID 34754326, 2021).
E. coli infection (1 paper, 2020). "After E. coli infection, JNK, Calpain 2, and Caspase-12 proteins were displayed mainly in the cytoplasm of inflammatory cells and pulmonary epithelial cells in the infected areas." (PMID 32685099, 2020).
esophageal cancer (1 paper, 2025). A primary or metastatic malignant neoplasm involving the esophagus. "Another study has indicated that CAPN1/CAPN2 can facilitate cisplatin-induced pyroptosis in esophageal cancer." (PMID 40520022, 2025).
glioma (1 paper, 2012). A benign or malignant brain and spinal cord tumor that arises from glial cells (astrocytes, oligodendrocytes, ependymal cells). "Cell invasion is a characteristic of most malignant tumors, and in glioma cells this process is often mediated by calpain-2, a calcium-dependent thiol proteinase, which consists of a catalytic subunit and a regulatory subunit." (PMID 22629380, 2012).
hearing loss (1 paper, 2022). "Three autophagy-related genes (Dram1, Fkbp1b, and Fos) were differentially expressed in the mild hearing loss group, whereas five autophagy-related genes (Dram1, Fkbp1b, Fos, Capn2, and Eef2) were differentially expressed in the severe hearing loss group." (PMID 35463035, 2022).
heart failure (1 paper, 2021). Inability of the heart to pump blood at an adequate rate to meet tissue metabolic requirements. "A recent study also showed that calpain-2 cleaves junctophilin-2 in heart failure and that the C-terminal fragment of junctophilin-2 generated by calpain-2 translocates to the cardiomyocyte nucleus, which may promote isoproterenol-induced hypertrophy in cardiomyocytes." (PMID 34440793, 2021).
hyperlipidemia (1 paper, 2013). "Therefore, the inhibition of calpain-2 may decrease hyperlipidemia-induced β-cells apoptosis in T2DM." (PMID 23527285, 2013). "Furthermore, we found that calpain-2 is required for FFA treatments-induced cell apoptosis and activation of caspase-12 and caspase-3 in β-cells, which may account for cell apoptosis in hyperlipidemia induced T2DM." (PMID 23527285, 2013).